RNU6-803P (RNA, U6 small nuclear 803, pseudogene)
Gene: Small nuclear RNA gene on chromosome 19 (53,719,064 to 53,719,165, reverse strand). Ensembl gene ENSG00000251843.
Homologues: Orthologues: chimpanzee U6 (99% identical), guinea pig U6 (71% identical). Paralogues in human: RNU6-751P (79% identical), RNU6-1175P (76% identical), RNU6-1067P (75% identical), RNU6-116P (75% identical), RNU6-1316P (75% identical), RNU6-1 (75% identical), RNU6-1145P (75% identical), RNU6-165P (75% identical), RNU6-16P (75% identical), RNU6-195P (75% identical), RNU6-2 (75% identical), RNU6-251P (75% identical), and 1286 more.